TERT (telomerase reverse transcriptase)
Diseases named in the same sentence as TERT in open-access papers (continued):
Sharing a sentence is not in itself a finding about the gene and the disease.
melanoma (continued). "This variant occurs in approximately 5% of melanoma cases and helps explain why, during the early transitional stages of melanoma, telomeres in cells with TERT promoter mutations may continue to shorten, despite the mutation’s presence." (PMID 39871386, 2025). "There was a TERT promoter mutation, which is a well‐characterized driver mutation in melanoma." (PMID 40090763, 2025). "In melanoma, TERT promoter mutations are associated with worse clinical outcomes." (PMID 40981345, 2025). "Moreover, BRAF-mutated melanomas with increased TERT expression were observed to be resistant to BRAF and MEK inhibitors." (PMID 40361989, 2025). "Beyond a relatively small number of hotspots (e.g., the TERT promoter, which is known to be highly mutated across cancer types) the majority of the identified hotspots (n = 281, 70%) are exclusively mutated in melanoma alone." (PMID 39367275, 2024). "Apart from TERT, all other somatic eQTL associations were melanoma-specific." (PMID 39367275, 2024). "Finally, TERT mutation was seen in 75 % of melanoma metastases of tumors logged in the GENIE database, with significant enrichment in metastases versus primary tumors (p < 0.001)." (PMID 38158497, 2024). "Mutations in the TERT promoter region are associated with reduced disease-free survival, increased tumour recurrence, and a higher rate of metastasis in melanoma: in other words, these mutations increase TERT expression, which helps cancer cells grow and survive." (PMID 39199954, 2024). "Therefore, the TERT-p mutation status can potentially differentiate between nevi and melanomas with fairly high specificity, but it shows a low sensitivity for detecting melanoma in some studies." (PMID 38247727, 2024). "TERT mutations are common in melanoma (69%) and are associated with a poor prognosis." (PMID 39204387, 2024). "While certain cancer types (ie, HNC and HPBC) exhibited a higher rate of TERT promoter mutations in primary tumor samples compared to metastatic samples, mutations were more prevalent in metastatic samples of melanoma and thyroid cancer compared to primary tumors." (PMID 37462445, 2024). "TERT promoter mutations are present in about 43% of sequenced melanoma samples." (PMID 39200315, 2024). "Melanomas arising from small or medium CN often harbor an additional TERT-p mutation." (PMID 38247727, 2024). "TERT-mutated melanoma patients had a significantly worse OS compared to wild-type ones." (PMID 39530091, 2024). "Furthermore, TERT mutations are being studied as possible therapeutic targets due to their role in melanoma progression." (PMID 38667446, 2024). "TERT mutations adversely affected the survival of patients with melanoma." (PMID 39530091, 2024). "Interestingly, in melanoma and thyroid papillary carcinoma, TERT mutation is widely found to be associated with BRAF p.V600E mutations." (PMID 36831610, 2023). "Over 60% of UV-related melanomas exhibit TERT promoter mutations." (PMID 37239381, 2023). "Also, TERT expression has been suggested to be an independent prognostic marker associated with poor survival in human cancer patients beyond melanoma." (PMID 37418389, 2023). "As the role of TERT expression in malignant melanoma and the non-canonical functions of TERT remain understudied, we aimed to extend the current knowledge on the impact of TERT promoter mutations and expression alterations in tumor progression by analyzing several highly annotated melanoma cohorts." (PMID 37418389, 2023). "To understand how TERT promoter mutations could be associated with resistance to targeted therapy in melanoma, we conducted translational and in vitro studies." (PMID 37296851, 2023). "TERT, which encodes the telomerase reverse transcriptase subunit of the telomerase enzyme is another important predisposing mutation for the development of melanoma." (PMID 38076247, 2023).
melanoma (continued). "Thus, the conclusions of three predictions (PWMs_full, C1_full, C1fC2_25) are the same: ETS-related factors significantly increased their binding affinity at the mutation block near the promoter of the TERT gene in the melanoma cohort." (PMID 37520692, 2023). "Finally, we demonstrated that the inhibition of TERT reduced the growth of BRAF-mutated melanoma including resistant cells." (PMID 37296851, 2023). "Finally, we established that TERT inhibition is a therapeutic option in V600E-BRAF-mutated melanoma with acquired resistance to BRAF inhibition." (PMID 37296851, 2023). "Four additional melanoma somatic mutation hotspots (> 3 mutations) were present in the assayed regions: TERT, encoding one subunit of telomerase and known to be frequently activated by somatic promoter mutations in cancer, and three ETS-related sites (RPL13A, AP3D1 and EGR1)." (PMID 37169761, 2023). "Furthermore, specific mutations in the TERT promoter have been found to frequently coexist with BRAF V600E variation in melanoma and observed to affect the disease-free survival of cancer patients." (PMID 38033865, 2023). "Associations with the presence of TERT promoter mutations revealed an overlap of 30 genes in the three bulk RNA-seq cohorts (in melanoma and across entities), of which six genes were consistently up- or down-regulated (up: ARL17A, FBF1, KAZALD1, PRAF2; down: PLEKHB2, RASGRP3)." (PMID 37418389, 2023). "An example of the essential impact of TERT mutation on the early stages of melanomagenesis was demonstrated by Bastian and his group, who suggested a stepwise accumulation of mutations during the process of nevus to melanoma transformation." (PMID 36834954, 2023). "As we had demonstrated that TERT was involved in the reactivation of the MAPK pathway in BRAF-mutated melanoma cell line, we hypothesized that the combination of 6-thio-dG with BRAF inhibitor could have some additional inhibitory effects." (PMID 37296851, 2023). "The assay also provides the status of TERT, a frequent somatic driver mutation in melanoma." (PMID 38076247, 2023). "Furthermore, regarding the site of origin, differences also exist in the same subgroup: in an earlier study, we concluded that NRAS and TERT promoter mutation rates were significantly higher in sinonasal than in oral mucosal melanomas of the head and neck." (PMID 35642348, 2023). "Interestingly, inhibition of TERT reduced growth of BRAF-mutated melanoma including resistant cells." (PMID 37296851, 2023). "Short telomeres and TERT aberrations are associated with poor survival in melanoma." (PMID 37239381, 2023). "The C228T and C250T TERT promoter mutations are frequently found in melanoma cases." (PMID 37504268, 2023). "In each of the following sections, we start at the genomic level by analyzing the role of TERT promoter mutations in malignant melanoma and extend the analysis to the transcriptomic level by examining the impact of TERT expression on clinical and molecular associations." (PMID 37418389, 2023). "TERT promoter mutations and TERT expression are proposed as prognostic biomarkers in melanoma and TERT promoter mutations might be predictive under anti-CTLA4 therapy." (PMID 37418389, 2023). "Correspondingly, TERT mutations are significant elevated in melanomas with RB1 pathway alterations." (PMID 34983823, 2022). "Combined with previous research, it is speculated that tandem mutations may cause greater genomic instability than common TERT promoter mutations and therefore are associated with the worst survival rate of melanoma." (PMID 35903534, 2022). "We infer that that TERT -146 may be one of the causal mutations that affects melanoma growth, migration and invasion, and apoptosis." (PMID 35053139, 2022). "TERT promoter mutations are biomarkers of poor melanoma outcomes, and mutations leading to increased TERT expression may play a role in tumor growth." (PMID 35903534, 2022).
melanoma (continued). "TERT promoter mutations are prevalent in malignant melanoma but rarely in melanocyte nevus." (PMID 35903534, 2022). "We want to know whether the TERT promoter revertant mutation inhibits growth of melanoma via the Wnt/β-Catenin signaling." (PMID 35053139, 2022). "Further analyses into the specific mutated regions of TERT identified upstream promoter, downstream, and intronic regions as having increased mutation frequency in melanomas that also carry mutations in the RB1 pathway compared with tumors without RB1 pathway alterations." (PMID 34983823, 2022). "Mutations in the TERT gene are characteristic of both sporadic and hereditary melanomas." (PMID 35465855, 2022). "In melanoma, TERT T349C has been reported to modify the effects of somatic TERT promoter mutations leading to increased survival in melanoma and this may be mediated through a lengthening of telomeres." (PMID 35494035, 2022). "TERT promoter mutation is a multiple event and is the most common noncoding mutation in melanoma." (PMID 35903534, 2022). "Furthermore, genetic testing and next-generation sequencing can diagnose melanoma patients with TERT promoter mutations." (PMID 35903534, 2022). "However, further independent prospective studies are needed to assess the reliability of TERT promoter mutations as an independent prognostic factor for melanoma." (PMID 35903534, 2022). "In addition to successful detection of TERT promoter mutations our current custom melanoma panel performed favorably, based on tissue concordance (76%), 95MDAF (0.2%) and significant correlation with ddPCR, when compared to previously published custom panels." (PMID 35494035, 2022). "Additionally, the PLA recently incorporated TERT, a high-risk driver mutation key in early-stage melanoma, as an add-on DNA-based molecular assay." (PMID 36579219, 2022). "TERT promoter mutations also have a certain effect on the survival of melanoma patients." (PMID 35903534, 2022). "This distribution of TERT promoter mutations aligns with previous studies on melanoma." (PMID 35494035, 2022). "Some studies have shown that TERT promoter mutations can promote the occurrence and development of melanoma, invasion, and metastasis of melanoma and are related to the poor prognosis and survival of melanoma patients." (PMID 35903534, 2022). "Also, melanoma patients with TERT promoter mutations have shorter disease-free survival than patients without such mutations." (PMID 35903534, 2022). "TERT mutations were first found in melanoma and later reported in thyroid cancers." (PMID 33562809, 2021). "The melanomas that cells have mutations in the TERT gene are accompanied with a poor prognosis." (PMID 34203771, 2021). "However, we found pathological mutations in the PTPN11, NF1, CUX1, IKZF1 gene and TERT promoter, which better fit a diagnosis of a melanoma than of lung cancer." (PMID 34819052, 2021). "The TERT promoter mutations in previous studies have been shown to associate with markers of poor prognosis, increased tumor growth, hematogenous dissemination, and define the subsets of melanoma patients with poor disease-free and disease-specific survival." (PMID 34680367, 2021). "Activating TERT promoter mutations result in increased gene expression and have been associated with increased Breslow thickness and the presence of ulceration and mitoses in melanoma patients." (PMID 34898573, 2021). "In addition, TERT promoter mutation, detected in about half of melanoma cases, was independently associated with the prognosis of melanoma patients and of patients with other tumors." (PMID 34209415, 2021). "The promoter’s mutations of the TERT gene are observed in 77% of the pecursor lesions of the melanoma and in a relatively early stage of their genesis, as well as in a large part of the cells of the melanoma itself." (PMID 34203771, 2021).
melanoma (continued). "In addition to the loss of these tumor suppressor genes, the acquisition of the TERT promoter mutations is necessary for melanomas to become replicative immortal." (PMID 34359771, 2021). "The TERT gene (Telomerase Reverse Transcriptase in 5p15) encodes the catalytic subunit of the telomerase enzyme implicated in the maintenance of telomere length, and it is known to be somatically mutated in a variety of tumors, including melanoma." (PMID 34356093, 2021). "Our result showed that only male melanoma patients with TERT mutation had longer median OS." (PMID 32915164, 2020). "Notably, for Melanoma and Hepatobiliary cancer, TERT mutation frequency was higher in male patients than female patients." (PMID 32915164, 2020). "Furthermore, despite being described in only two families, TERT mutations have been described as high-risk melanoma susceptibility genes." (PMID 32276436, 2020). "In conclusion, using the cBioPortal database, we identified that TERT mutation may serve as a sex-specific cancer biomarker and TERT mutation frequency of melanoma was higher in male patients." (PMID 32915164, 2020). "BRAF, NRAS and TERT mutations occur in more than 2/3 of melanomas." (PMID 33122747, 2020). "Finally, we explored the effect of TERT mutation and sex disparity on the efficacy of immunotherapy in pan cancer, especially melanoma." (PMID 32915164, 2020). "Concerning ctDNA molecular features, mutations in the BRAF, NRAS, KIT and TERT genes are considered melanoma-driving mutations and their detection could help to adapt the strategy for patient monitoring." (PMID 32295074, 2020). "Urothelial carcinoma and melanoma also showed worse prognosis in patients harboring TERT mutation." (PMID 32850388, 2020). "With the availability of the cBioPortal database, we identified that TERT mutation may serve as a sex-specific cancer biomarker and TERT mutation frequency of melanoma was higher in male patients." (PMID 32915164, 2020). "Although it can be difficult to target a promoter variant, TERT silencing has been successful in NRAS mutant melanoma and might be applied to other tumors in the future." (PMID 32455687, 2020). "We proposed to standardize a liquid biopsy platform to identify hotspot mutations in BRAF, NRAS and TERT in plasma samples from advanced melanoma patients and investigate whether it was associated to clinical outcome." (PMID 33122747, 2020). "However, in melanoma and keratinocyte cancers, the −146 C > T is the most frequent TERT promoter mutation." (PMID 32409749, 2020). "This custom ddPCR panel would have a predicted coverage of ~80% of cutaneous melanomas based on the skin cutaneous melanoma TCGA dataset which gives a BRAF/NRAS coverage of ~70% and the fact that TERT promoter mutations are found in around ~29% of BRAF wild-type melanoma patients." (PMID 32785074, 2020). "In addition, a high frequency of mutations in the promoter region of TERT gene has been found in melanoma patients with a frequency ranging from 50 to 80% in several studies, including Brazilian populations." (PMID 33122747, 2020). "Moreover, we also found that TERT mutation frequency of Melanoma and Hepatobiliary cancer was higher in male patients than female patients." (PMID 32915164, 2020). "Notably, in the subgroup analysis of monotherapy and combination ICI treatment, only in the anti‐cytotoxic‐T‐lymphocyte‐associated antigen 4 (anti‐CTLA4) group, patients with TERT mutations had a better prognosis, especially for melanoma." (PMID 32810393, 2020). "Therefore, we further explored the predictive value of TERT mutation on the efficacy of anti‐CTLA4 treatment in the melanoma group." (PMID 32810393, 2020). "For example, recurrent mutations on the promoter of the TERT gene generated ETS factor binding sites and fluctuated TERT expression, factors that encode a catalytic subunit of the enzyme telomerase so that the risk of melanoma development increased because cell fates were made instable." (PMID 32158610, 2020).
melanoma (continued). "Furthermore, BRAF and NRAS mutations are mutually exclusive, as well as TERT C250T and C228T, and then, a maximum of two mutations will be tested in plasma for each melanoma patients, making feasible the dPCR approach proposed in this study." (PMID 33122747, 2020). "Besides activating mutations of the MAPK pathway, radial growth melanomas are more consistently acquiring activating mutations in the TERT promoter (about 80% of the cases) in respect with dysplastic nevi." (PMID 30934534, 2019). "TERT promoter mutations may therefore be an earlier event in the pathway to melanoma than first thought." (PMID 31861163, 2019). "TERT promoter mutations have been shown to correlate with poorer outcomes in subsets of melanoma patients with BRAF/NRAS mutations, and this may serve as a potential future biomarker." (PMID 31861163, 2019). "However, our results and the external validation in a group of progressed primary melanomas support the previously reported finding of a worse outcome in TERT-mutated trunk melanomas." (PMID 30934988, 2019). "Since the first report of melanoma, > 30 types of tumors have been found to contain TERT promoter mutations, hepatocellular carcinoma (41%), thyroid cancer (11–43%), ovarian clear cell carcinoma (16%), bladder cancer (63%), and phyllodes tumors of the breast (65%)." (PMID 29222734, 2018). "Our data suggest that in addition to its cannonical role, TERT may also possess a telomere length-independent role promoting melanoma survival, as catalytically impaired and telomere elongation-deficient TERT can protect cells from loss of oncogenic NRAS." (PMID 29695835, 2018). "Two exceptions might be the CDKAL1 and TERT melanoma risk loci, that lie near the orthologous SCC7 and SSC16 ulceration-associated regions, respectively." (PMID 29963229, 2018). "The MM lesion carried a BRAFV600E and a TERT promoter mutation.As the family story was consistent with a genetic predisposition to cancer, we performed mutational analysis of genes involved in familial melanoma and CLL, and of BRCA1 and BRCA2." (PMID 29371889, 2018). "Moreover, a recent study showed that the prognostic effect of TERT promoter mutation was different for each melanoma subtype." (PMID 29222734, 2018). "Additionally, other mutations in the TERT promoter have been found in melanoma as well as in other cancer types such as ovarian, follicular thyroid, and meningiomas." (PMID 29456552, 2018). "Primary melanomas with known TERT mutation status were now also analyzed by TERT IHC." (PMID 29262649, 2017). "A more exhaustive understanding of the different molecular mechanisms leading to increased TERT expression may guide development of prognostic assays to stratify AYA melanoma patients according to clinical risk." (PMID 28378855, 2017). "TERT (telomere reverse transcriptase) and some other components of the telomere maintenance complex have been identified as risk genes for several cancer types, including melanoma." (PMID 29081790, 2017). "Median relative TERT mRNA level was significantly higher in cases of conventional melanoma than in nevoid or spitzoid samples (P = 1.2 × 10−6) and in tumors harboring TERT promoter mutation and/or hypermethylation than those without either aberration (P = 0.046)." (PMID 28378855, 2017). "Finally, TERT promoter mutations were more frequent in mixed than in pure desmoplastic melanoma subtypes (54% vs. 23%)." (PMID 29156643, 2017). "Co-occurrence with telomerase reverse transcriptase (TERT) promoter mutations (found in 38% of melanomas) was observed to be more commonly associated with high-risk clinicopathologic characteristics, suggesting potential interplay of TERT promoter and BRAF mutations in melanoma evolution." (PMID 29179523, 2017).